OR5D14 (olfactory receptor family 5 subfamily D member 14)
Description:
Odorant receptor.
Synonyms: OR11-141; OR11-150
Tractability: Antibody: its Gene Ontology location is reachable by antibodies, with high confidence; UniProt places it where antibodies can reach, with medium confidence; UniProt predicts a signal peptide or a membrane-spanning region.
Gene: Protein-coding gene on chromosome 11 (55,795,556 to 55,796,500, forward strand). Ensembl gene ENSG00000186113.
Subcellular location: Cell membrane
Pathways (Reactome):
Sensory Perception: Expression and translocation of olfactory receptors; Olfactory Signaling Pathway
Gene Ontology:
Molecular function: olfactory receptor activity; G protein-coupled receptor activity
Biological process: G protein-coupled receptor signaling pathway; sensory perception of smell; detection of chemical stimulus involved in sensory perception of smell
Cellular component: plasma membrane; membrane
Genetic constraint (gnomAD): Loss-of-function variants: 1 observed, 0.47 expected, observed/expected ratio (o/e) 2.11. That is too few expected variants to judge how well the gene tolerates losing a copy. Missense variants: 454 observed, 382.2 expected, observed/expected ratio (o/e) 1.19, 90% interval 1.1 to 1.28. Synonymous variants: 181 observed, 141.98 expected, observed/expected ratio (o/e) 1.27, 90% interval 1.13 to 1.44.
Homologues: Orthologues: chimpanzee OR5D14 (99% identical), macaque OR5D14 (94% identical), pig OR5D14 (88% identical), dog OR5D14 (88% identical), mouse Or5d14 (82% identical), rat Or5d14l1 (82% identical), mouse Or5d36 (78% identical), rat Or5d14 (77% identical). Paralogues in human: OR5D18 (71% identical), OR5D16 (68% identical), OR5D3 (64% identical), OR5D13 (61% identical), OR5L1 (56% identical), OR5L2 (55% identical), OR5I1 (51% identical), OR5AP2 (50% identical), OR5B12 (50% identical), OR5B21 (50% identical), OR8U3 (50% identical), OR5AR1 (49% identical), and 84 more.